GPR35 (G protein-coupled receptor 35)
Diseases named in the same sentence as GPR35 in open-access papers (continued):
Sharing a sentence is not in itself a finding about the gene and the disease.
GPR35 also shares sentences with these, for which no sentence is quoted: fatty liver (2 papers); stomach cancer (2); Alzheimer disease (1); behavioral disorders (1); brachydactyly (1); cardiac ischemia (1); cognitive disorder (1); colon adenoma (1); coronary artery calcification (1); Crohn disease (1); glioblastoma (1); glioma (1); gout (1); heart disease (1); hepatocellular carcinoma (1); kidney cancer (1); liver cancer (1); liver disease (1); melanoma (1); metabolic syndrome (1); neurodegenerative disease (1); Pruritus (1); Sepsis (1); viral infection (1).